MSH6 (mutS homolog 6)
Diseases named in the same sentence as MSH6 in open-access papers (continued):
Sharing a sentence is not in itself a finding about the gene and the disease.
tumor (continued). "Factors other than tumor immunity, such as the reduction of MSH6/2 expression and cell cycle regulators, could play a more important role in the proliferation and invasiveness in SCAs and NCAs." (PMID 32325698, 2020). "However, this tumor also harbored a hypermutator phenotype, involving the MSH6 gene and the MMR mechanism, allowing to design a new therapeutic strategy." (PMID 31376079, 2020). "The lack of MSI within the tumor despite a known germline mutation in MSH6 and heterogeneous expression by immunohistochemistry is not an uncommon finding." (PMID 31307558, 2019). "The highest level of intra-tumor heterogeneity in MMR protein expression was observed for MSH6." (PMID 31360876, 2018). "Immunohistochemistry analysis for MSH6 in the tumor of patient HPC332 showed normal MSH6 expression, thus reducing the likelihood that the MSH6 c.1729C>T variant is a PrCa risk factor and rendering the ATM mutation c.8560C>T the most likely risk variant in this patient." (PMID 29659569, 2018). "After macrodissection of these areas, pyrosequencing clearly confirmed the MSH6 mutation, identified in the whole exome sequencing, in tumor tissue with lack of MSH6 protein expression." (PMID 28146430, 2017). "Due to the very high amount of private mutations in the peripheral sample of patient 4 compared to all other samples and as the MSH6 mutation was classified as “putative driver mutation”, we wanted to further study its possible contribution to the pathogenesis and ITH of this tumor." (PMID 28146430, 2017). "About 60% of tumour cells showed nuclear expression of MSH6." (PMID 28284009, 2017).
tumor (continued). "Cluster three, which contained expressed mutations in BRAF (K601E) and MSH6 (nonsense), made up 92% of the baseline tumour, but was absent in the post-treatment samples, suggesting that it harboured enhanced susceptibility to oestrogen deprivation." (PMID 27502118, 2016). "Recurrent tumor cells acquired resistance to the nimotuzumab and TMZ combination treatment, which was associated with reduced expression of the mismatch repair proteins, MSH6 and MLH1." (PMID 26778701, 2016). "Two cases with mutations MSH6 (ages 56 and 61 years) did not fulfill the rBG criteria and no other synchronous tumor was present at diagnosis." (PMID 24244552, 2013). "These antigenic epitopes could be good candidates for immunotherapy, because mutations in the MSH3 gene, along with others, e.g. TGFβRII, BAX and MSH6, appear to play an active role in tumor progression." (PMID 22110587, 2011). "In only one of these tumours (a tumour with an MSH6 germline mutation and absence of MSH6 protein staining, but presence of MLH1 protein staining), we detected incomplete MLH1 promoter methylation (about 60%)." (PMID 17453009, 2007). "The aim of this study was to establish the prevalence of MSH6 mutations in HNPCC suspected patients without MSI in their tumours to investigate the value of MSI analysis to detect MSH6 mutations." (PMID 17117178, 2006). "However careful consideration of previous studies is required as part of the conclusions are based on MSH6 missense mutations of unknown pathogenecity or testing a sporadic tumour within an HNPCC family (a phenocopy) as suggested by positive immunostaining of MSH6 in the tumour." (PMID 17117178, 2006). "One tumour, a CRC developed at age 53, exclusively showed loss of the MSH6 protein." (PMID 17117178, 2006). "In this study, not one pathogenic germline MSH6 mutation was detected in HNPCC suspected patients with a non-MSI-high CRC or HNPCC-related tumour." (PMID 17117178, 2006). "However, no significant changes were observed in the other mismatch repair genes, MLH1 and MSH6 in either tumor type." (PMID 16026610, 2005). "Our experimental results in conjunction with the clinical characteristics of the patients provide evidence that most MSH6 missense mutations found in a population-based case series of patients with MSI positive tumours are unlikely to be deleterious." (PMID 15354210, 2004). "Interestingly, we found an enrichment of high MSH6 tumours in the CN-high subgroup." (PMID 36482191, 2023). "One of the four MSH6 variants was a missense variant (c.3259C>T), which has been associated with low levels of MSI, suggesting it might have lost MMR function while retaining MMR protein expression in a subset of the tumor cells (30%)." (PMID 37143941, 2023).
tumor (continued). "From a total of 6830 tumor samples from 6527 individual patients that underwent tumor DNA sequencing, 584 unique tumor variants were identified in the gene list of interest (ATM, BRCA1, BRCA2, MLH1, MSH1, MSH6, PALB2 and PMS2) from 503 unique tumor samples/patients during the study period." (PMID 36261688, 2023). "For one of the two MSI‐H/EMAST‐negative tumours, immunohistochemical data were available and an isolated loss of MSH6 expression was found, which may be related to the negative instability pattern specifically observed at tetranucleotides in this tumour." (PMID 35099128, 2022). "In addition, isolated loss of MSH6 was found in one MSS/MSI‐L and EMAST‐negative tumour." (PMID 35099128, 2022). "Taking these cancer-preventive measures into account, we assessed the cumulative risk of first onset of pre/neoplasia (cancer and polyps combined) by age in carriers of the MSH6 variant alone over non-carriers of either MMR variant and did observe a significantly increased risk." (PMID 36612224, 2022). "However, clinical documentation of a primary lesion at young age, immuno-histochemical MSH6 deficiency of the tumor cells and a DNA methylation profile indistinguishable from other samples of this group are still compatible with a Lynch-associated case." (PMID 33216206, 2021). "Altogether, our pan-cancer research has suggested that the MSH6 expression level was closely related to the carcinogenesis and prognosis of certain tumors, which helps to know the effect of MSH6 in tumorigenesis from the point of view of clinical tumor samples." (PMID 34941572, 2021). "Hence, to clarify the relationship between MSH6 expression and tumor-infiltrating immune cells, we investigated the relationship between MSH6 expression and cancer-associated fibroblasts, as well as CD8+ T-cells immune infiltration levels of different cancer types." (PMID 34941572, 2021). "Besides, MSH6 was lowly expressed in normal tissues and highly expressed in tumor tissues." (PMID 32746792, 2020). "In addition to these two more common pattern of MMR protein expression in tumour with MMRD, other less frequent patterns, such as isolated losses of PMS2 and MSH6 also occurred in LS patients due to germline mutations of PMS2 and MSH6, respectively." (PMID 32664968, 2020). "A previous in vitro study also suggested MSH6-A25S is not pathogenic; it could be that the tumor arose due to a missed somatic mutation." (PMID 28531214, 2017).
tumor (continued). "However, tumours that have a deficiency in MSH6 often do not show instability in dinucleotide repeats and therefore risk being classified as MSI-L or even MSS when analysed with the NCI panel containing only two potentially unstable mononucleotide repeats." (PMID 21081928, 2010). "Tumours of MSH6 mutation carriers lacked MSH6, and those of PMS2 mutation carriers lacked PMS2." (PMID 17453009, 2007). "Some genes containing these repetitive sequences code for proteins involved in tumor suppression (e.g., TGFBR2), cellular proliferation, DNA repair (e.g., MSH3, MSH6), and apoptosis (e.g., BAX)." (PMID 41214301, 2026). "Genes involved in tumor suppression (e.g., TGFBR2), cell proliferation, DNA repair (e.g., MSH3, MSH6), and apoptosis (e.g., BAX) contain these repetitive sequences in the coding regions, where alterations tend to develop." (PMID 41214301, 2026). "In one immunohistochemical analysis involving 28 cases in Iran, researchers examined PD-L1 expression both within tumor cells and the surrounding peritumoral inflammatory infiltrate, alongside MMR status determined through MSH6 and PMS2 markers." (PMID 41020848, 2025). "Although MSH6 expression was preserved, this pattern suggests a more complex MMR dysfunction in the tumor tissue." (PMID 41480141, 2025). "Analysis of TCGA database (accession number: phs000178) revealed increased PSI values for ACTA2, AREG, BRCA1, DDX5, MSH6, and PARP1 in tumor tissues compared to adjacent tissues." (PMID 39773744, 2025).
tumor (continued). "Because of the relatively low number of LS and MSH6 tumours in both EC cohorts, we also analysed CRC cohorts and identified small but significant reductions in VAFs in both MSH6 and LS tumours." (PMID 39682157, 2024). "and ID_111 (MSH6 c.1153_1155del p.(Arg385del)), demonstrated MSI-H/dMMR by tumor sequencing and a second hit in their respective CRCs; however, both CRCs were pMMR by IHC, suggesting a false negative MMR IHC result." (PMID 37894291, 2023). "Significant SNV alterations were observed in BRCA2, ACACB, BRCA1, MSH6 and IFI16 in most tumour types." (PMID 37660060, 2023).